SOCS3 (suppressor of cytokine signaling 3)
Diseases named in the same sentence as SOCS3 in open-access papers (continued):
Sharing a sentence is not in itself a finding about the gene and the disease.
osteosarcoma (8 papers, 2014 to 2023). A usually aggressive malignant bone-forming mesenchymal neoplasm, predominantly affecting adolescents and young adults. "Piperlongumine, a long-pepper-derived amide alkaloid, suppresses the proliferation of osteosarcoma cells by downregulating miR-30d-5p and upregulating its target, the suppressor of cytokine signaling 3 (SOCS3)." (PMID 36612314, 2023). "LncRNA THAP9-AS1 is highly expressed in osteosarcoma tissues and increases methylation at the promoter region of the suppressor of cytokine signaling 3 (SOCS3), which activates JAK2/STAT3 signaling to reduce oxidative stress." (PMID 35625948, 2022). "By interacting with DNMTs, THAP9-AS1 modulates methylation patterns in the SOCS3 promoter region, paving the way for JAK2/STAT3 pathway activation and, consequently, osteosarcoma progression." (PMID 38140058, 2023). "Further studies revealed that exosomal miR-221-3p can inhibit suppressor of cytokine signaling 3 (SOCS3) and activate the JAK2/STAT3 signaling pathway to promote the growth and metastasis of osteosarcoma." (PMID 35592419, 2022). "Furthermore, the finding that simvastatin is capable of inducing SOCS-3 and CIS gene expression, shows the potential of the JAK/STAT pathway as a therapeutic target, reinforcing the efficacy of simvastatin as chemotherapeutic drug for the treatment of osteosarcoma." (PMID 24489959, 2014). "Furthermore, the finding that simvastatin is capable of inducing SOCS-3 and CIS genes expression shows the potential of the JAK/STAT pathway as a therapeutic target, reinforcing the efficacy of simvastatin as chemotherapeutic drug for the treatment of osteosarcoma." (PMID 24489959, 2014).
Stroke (8 papers, 2018 to 2025). Sudden impairment of blood flow to a part of the brain due to occlusion or rupture of an artery to the brain. "Reducing SOCS3 levels in the brain is reported to polarize macrophages towards the M2 phenotype and promote the resolution of post-stroke inflammation." (PMID 40362325, 2025). "We also noted a higher expression of Socs3 (suppressor of cytokine signaling 3) in PPARα KO brains after stroke." (PMID 40362325, 2025). "For instance, the miR-3473b has been shown to participate in post-stroke neuroinflammation injury by targeting the suppressor of cytokine signaling 3 (SOCS3), a crucial negative regulator of Th2-mediated allergic responses." (PMID 36572876, 2022). "In conclusion, induction of miR-3473b, which is likely targeted to SOCS3, contributes to stroke pathogenesis by enhancing post-stroke neuroinflammation injury." (PMID 29317607, 2018). "Further blockade or supplement of SOCS3 studies are needed to demonstrate the role of SOCS in miR-3473b contribution to stroke pathology." (PMID 29317607, 2018). "Some other findings indicated that the downregulation of Socs3 in the microglia/macrophages could lead to a marked bias toward the M2 phenotype and ameliorate the inflammation, which could promote neuroprotective effects after stroke." (PMID 36605216, 2022).
triple-negative breast carcinoma (8 papers, 2017 to 2026). An invasive breast carcinoma which is negative for expression of estrogen receptor (ER), progesterone receptor (PR), and human epidermal growth factor receptor 2 (HER2). "SOCS3 plays an important role in tumor development where its downregulation has been implicated in the pathogenesis of various solid tumors such as triple-negative breast cancer." (PMID 38533493, 2024). "SOCS3 can also negatively control the STAT3/NF-κB signaling pathway in a triple-negative breast cancer model." (PMID 28228755, 2017). "Suppressor of Cytokine Signaling 3 (SOCS3) is a pivotal negative regulator of the JAK/STAT pathway, and its loss or silencing is frequently associated with hyperactivated STAT3 signaling in aggressive cancers, including Triple-Negative Breast Cancer (TNBC)." (PMID 42077828, 2026). "miR-483-5p has also been found to have a carcinogenic role in triple-negative breast cancer in that it inhibits SCOS3 (suppressor of cytokine signaling 3) gene expression that may trigger the pathway of STAT3, NF-κB, and primary inflammatory cytokines such as TNF-α, IL-6, MCP-1, and IL-1β." (PMID 37298699, 2023). "Additionally, miR-455-5p promotes triple-negative breast cancer growth and immune evasion by targeting SOCS3, a negative regulator of cytokine signalling suggesting that microRNA-mediated modulation of ­cytokine pathways could influence responses to IL-33/ST2 and PD-1/PD-L1 co-inhibition." (PMID 41284319, 2025).
head and neck squamous cell carcinoma (7 papers, 2010 to 2022). A squamous cell carcinoma that arises from any of the following anatomic sites: lip and oral cavity, nasal cavity, paranasal sinuses, pharynx, larynx, and salivary glands. "Epigenetic silencing of SOCS3 has been shown in head and neck squamous cell carcinoma (HNSCC), which is associated with increased activation of STAT3." (PMID 23028842, 2012). "SOCS3 hypermethylation has been observed in cholangiocarcinoma and head and neck squamous cell carcinoma." (PMID 36551618, 2022). "Moreover, loss of SOCS3 expression has been described in head and neck squamous cell carcinoma (HNSCC)." (PMID 27367272, 2016).
Myocardial fibrosis (7 papers, 2020 to 2024). "For example, in diastolic heart failure (DHF) rat models, silencing the SOCS3 gene by administration of adeno-associated virus 9-mediated RNA interference targeting SOCS3 (AAV9-SOCS3 siRNA) significantly reduced myocardial fibrosis and inflammatory responses and improved cardiac function." (PMID 38886500, 2024). "Furthermore, SOCS3 ablation in LepR-expressing cells caused an increase in the relative collagen area of the heart in both young adult and middle-aged mice, which indicates the development of myocardial fibrosis." (PMID 35742928, 2022). "Hypermethylation of suppression of cytokine signaling 3 (SOCS3) promoter via DNMT1 downregulates SOCS3 expression levels in diabetic hearts and stimulates fibroblast activation and myocardial fibrosis." (PMID 37504569, 2023). "A previous study demonstrated that silencing Socs3 in a rat diastolic heart failure model was able to significantly diminish myocardial fibrosis and the inflammatory response." (PMID 33194355, 2020). "It suppresses TNF-α and IL-1β synthesis by activating one of its target genes, the Suppressor of Cytokine Signaling (SOCS)-3, thus preventing from collagen synthesis by activated myofibroblasts and from myocardial fibrosis." (PMID 32117843, 2020). "Aboulhoda studied age-dependent SOCS3 expression and myocardial fibrosis, and found that SOCS3 activity was correlated with myocardial fibrosis." (PMID 33194355, 2020). "Additional studies suggested that SOCS3 gene silencing in rats with heart failure greatly decreased myocardial fibrosis as well as the inflammatory response, leading to advancement of heart function." (PMID 33224271, 2020).
neuroblastoma (7 papers, 2008 to 2025). Neuroblastoma (NB) is the most common solid, extracranial childhood tumor. "Our findings are corroborated by two recent publications in rodent models that showed that IL-6 + sIL-6R can elevate joint sensory neuron firing in vivo and in vitro, as well as elevate Socs3 and Csf1 in a mouse neuroblastoma cell line." (PMID 40373045, 2025). "SOCS3-overexpression inhibited the JAK/STAT3-regulated protective effects of IGF1 against TNFα-induced lesions and led to neuroblastoma cell death, indicating the involvement of SOCS3 in cell survival." (PMID 29973864, 2018). "Levels of transcripts of SOCS3 was found to be increased with increased survival of neuroblastoma with leptin suggesting its role in neuroblastoma." (PMID 29278364, 2017). "In agreement with our finding endogenous SOCS-3 has been reported to block c-Jun phosphorylation and inhibit AP-1 activity in neuroblastoma cells." (PMID 24593195, 2014). "Socs3 suppresses AP-1 activity by inhibiting c-JUN phosphorylation in neuroblastoma cells." (PMID 29158586, 2017). "In this regard, SOCS3 overexpression has been shown to lead to neuroblastoma cell death." (PMID 18489773, 2008).
non-small cell lung carcinoma (7 papers, 2017 to 2025). A group of at least three distinct histological types of lung cancer, including non-small cell squamous cell carcinoma, adenocarcinoma, and large cell carcinoma. "In non-small cell lung cancer, Kremen2 drives tumor progression by preventing SOCS3-mediated ubiquitination of EGFR." (PMID 40170095, 2025). "In non-small cell lung cancers (NSCLC) it inhibits many tumor cell functions; while a downregulation of SOCS3 was found in gastric adenocarcinoma tissues and linked with enhanced risks of recurrent disease in BC patients." (PMID 35455455, 2022). "In non-small cell lung cancer (NSCLC), gemcitabine resistance can be transferred from cell to cell through exosomal miR-222-3p, which targets the promotor region of the SOCS3 gene." (PMID 35682901, 2022).
osteoarthritis (7 papers, 2014 to 2023). A noninflammatory degenerative joint disease occurring chiefly in older persons, characterized by degeneration of the articular cartilage, hypertrophy of bone at the margins and changes in the synovial membrane. "Socs3, a gene associated with the development of osteoarthritis, was suppressed by hydrostatic-only stimulation (CHP), which is the physical environment of normal cartilage tissue in non-weight-bearing areas." (PMID 37630168, 2023). "In cellular experiments, we examined the expression level of Socs3, which has been suggested to be associated with the onset of osteoarthritis." (PMID 37630168, 2023). "SOCS3 was also shown to play a role in modulating Th17 differentiation, as well as contributing to the progression of osteoarthritis and acantholysis." (PMID 38006062, 2023). "The activation of the AMPK/Gas6/MerTK/SOCS3 signal pathway by ozone also provides new theoretical evidence for ozone treatment of osteoarthritis." (PMID 38066599, 2023).
pulmonary fibrosis (7 papers, 2015 to 2025). Chronic progressive interstitial lung disorder characterized by the replacement of the lung tissue by connective tissue, leading to progressive dyspnea, respiratory failure, or right heart failure. "The study aimed to explore the effect of total flavonoids of Oxytropis falcata Bunge (FOFB) on the expression of p-JAK1/p-STAT1 and SOCS3 proteins in idiopathic pulmonary fibrosis (IPF)." (PMID 32908556, 2020). "Dysregulated SOCS3 activity may STAT3 signal transduction in fibroblasts/myofibroblasts in idiopathic pulmonary fibrosis (IPF)." (PMID 25888222, 2015). "To investigate the mechanism by which IL-27 acts in pulmonary fibrosis, we determined JAK, STAT1, STAT3, STAT5, and SOCS3 protein levels as well as STAT1, STAT3, and STAT5 phosphorylation levels using Western blot analysis." (PMID 25888222, 2015). "FOFB has a therapeutic effect on inflammation-mediated idiopathic pulmonary fibrosis, and its mechanism may be to inhibit the expression of p-JAK1 and p-STAT1 inflammatory proteins by upregulating the expression of SOCS3." (PMID 32908556, 2020). "IPF is an aging-related disease, but the role played by SOCS3 in pulmonary fibrosis has not been well-studied." (PMID 33194355, 2020).
small cell lung carcinoma (7 papers, 2015 to 2025). Small cell lung cancer (SCLC) is a highly aggressive malignant neoplasm, accounting for 10-15% of lung cancer cases, characterized byrapid growth, and early metastasis. "In small-cell lung cancer, low expression levels of cullin 5 (CUL5) and suppressor of cytokine signaling 3 (SOCS3) correlate with a highly metastatic phenotype and poor prognosis." (PMID 34131655, 2021).
steatosis (7 papers, 2015 to 2024). Increased lipid within the cytoplasm of cells. "This is also in accordance with our results as we detected significant positive associations between enhanced SOCS3 expression and steatosis grade." (PMID 37511764, 2023). "Liver-specific SOCS3 knockout mice fed an HFD had elevated hypothalamic SOCS3, increased food intake, reduced energy expenditure, and increased lipogenic capacity of the liver which leads to steatosis, inflammation, and metabolic deterioration." (PMID 36609306, 2023). "Namely, their study pointed out a significant effect in decreasing the degree of steatosis, decreasing the SOCS3 expression level, and increasing the Irs-1 expression level in Wistar rats treated with Exenatide." (PMID 35454311, 2022). "SOCS-3 also stimulates the expression of sterol regulatory element response sequence binding protein 1 c (SREBP-1c), associated with fatty acid metabolism in the liver, causing steatosis." (PMID 39457712, 2024). "In addition, mesenchymal stem cell-derived adipocytes from obese patients at different stages of NAFLD have impaired adipogenesis as liver steatosis augmented, showing a differential expression pattern in SOCS3, comparable to steatosis degree." (PMID 36674935, 2023). "There was no detectable difference in liver IL-6Ra expression from IL-6Ra KD and Cre+/- mice on either diet, likewise transcript abundance of Socs3, liver levels of which have been suggested to play an important role in steatosis, was unaltered by either diet or genotype." (PMID 35470093, 2022). "Further, we found that patients with steatosis grades 2 and 3 showed significantly higher pNRF2, SOCS3, and RIG1 expression levels than patients with steatosis grades 0 and 1 (p = 0.011; p = 0.008; p = 0.032)." (PMID 37511764, 2023). "Studies “in vitro” showed that activation of PPAR-γ and SOCS3 in Kupffer cells treated with saturated fatty acids participated in inflammation by releasing TNF-α and IL-6, and thus, this Kupffer cell dysfunction accelerated hepatocyte steatosis." (PMID 36674935, 2023).
atopic dermatitis (6 papers, 2011 to 2025). "Other studies, on the other hand, reported that in atopic dermatitis, including AD, overexpression of SOCS3 was associated with increased serum levels of IL-6 compared to control cases, suggesting a protective role of the SOCS3 protein." (PMID 38534350, 2024). "Furthermore, defined haplotypes of SOCS3 have been linked with atopic dermatitis in childhood cohorts." (PMID 24600449, 2014). "In contrast, histological analysis has highlighted a marked expression of both SOCS3 mRNA and protein in skin samples from patients with atopic dermatitis, suggesting that SOCS3 has a significant role in AD." (PMID 38534350, 2024). "In line with this, the increased SOCS3 expression in T cells correlated with the severity of asthma and atopic dermatitis or with the Th1-mediated condition psoriasis." (PMID 24600449, 2014). "Atopic dermatitis (AD) is known to increase the expression levels of SOCS3 and IL-4." (PMID 40005151, 2025). "It was shown elevated mRNA levels of SOCS-3 and GATA-3 are present in PBMC of patients with atopic dermatitis." (PMID 24138793, 2013).
B cell lymphoma (6 papers, 2014 to 2023). "MiR-30a in B-cell lymphoma targeted suppressor of cytokine signaling 3 (SOCS3), activating JAK-STAT3 signaling and promoting MDSC differentiation and immunosuppression." (PMID 36831498, 2023). "CD37, whose expression correlates with favorable prognosis, can protect against the development of B cell lymphoma by interacting with the suppressor of cytokine signaling 3 (SOCS3) to inhibit IL-6 signaling." (PMID 36941633, 2023). "Overexpression of miR-30a can specifically inhibit SOCS3 expression and enhance myeloid-derived suppressor cell differentiation and immunosuppression in mice with B-cell lymphoma." (PMID 32273831, 2020). "In another study, infection of heterogeneous human epithelial colorectal cancer cells (Caco2) with SARS-CoV also induced SOCS3 but to a lesser extent than the B cell lymphoma cell line." (PMID 33193390, 2020). "Transfection of a human B cell lymphoma (Toledo) with recombinant baculovirus vAtEpG5688 expressing amino acids 17-688 of SARS-CoV spike protein on the surface of the envelope induced over a 4-fold increase in SOCS3 over 48 h." (PMID 33193390, 2020).
Cachexia (6 papers, 2011 to 2023). Severe weight loss, wasting of muscle, loss of appetite, and general debility related to a chronic disease. "Interestingly, muscle IL-1β and SOCS3 gene expression were associated with several indices of cachexia, and several of these associations were altered by PDTC treatment." (PMID 27449092, 2016). "SOCS3 expression did not change further with cachexia progression." (PMID 25789991, 2015). "However, apart from its early induction in the weight—stable cancer mice, no further increase was observed in SOCS-3 with cachexia progression, highlighting a disconnect between STAT-3 and its downstream negative regulator with chronic IL-6 signaling." (PMID 25789991, 2015). "Interestingly, SOCS3 was found to be only minimally up regulated at the protein level in moderate cachexia in quadriceps and not at all in quadriceps in severe cachexia, while it was down-regulated in gastrocnemius samples in both moderate and severe cachexia." (PMID 21799891, 2011).
cervical cancer (6 papers, 2015 to 2023). A primary or metastatic malignant neoplasm involving the cervix. "Our data showed that altered expression of SOCS1or SOCS3 affected the radiation response of cervical cancer cells." (PMID 25849377, 2015). "However, they also show that overexpression of SOCS1 or SOCS3 confers radioresistance to cervical cancer cells." (PMID 37372319, 2023). "We show that altered SOCS1 and SOCS3 expression may contribute to the radiosensitive phenotype in cervical cancer." (PMID 25849377, 2015). "Later, in 2015, Kim’s group analyzed SOCS1, SOCS3, and SOCS5 in cervical cancer samples and HPV+ cervical cancer cell lines; they found that the expression of these three SOCS proteins decreased compared to tissues from the normal cervix." (PMID 37372319, 2023). "Ectopic expression of SOCS1 or SOCS3 conferred radioresistance to HeLa cells, which implied SOCS signaling regulates the response to radiation in cervical cancer." (PMID 25849377, 2015). "SOCS1, SOCS3, and SOCS5 expression was lower in cervix cancer than surrounding normal tissue, and the mRNA levels of SOCS genes were lower in cervical cancer cell lines than in normal cervix tissue or fibroblast cell lines." (PMID 25849377, 2015). "All cervical cancer cell lines tested showed lower expression of SOCS1, SOCS3, and SOCS5 than normal tissue or cell lines." (PMID 25849377, 2015). "All these results led to the conclusion that SOCS1, SOCS3, and SOCS5 expression ishigher in normal tissue than in cervical cancer, and support the possibility that downregulation of SOCS might contribute to the tumorigenesis or maintenance of cervical cancer." (PMID 25849377, 2015). "Wild-type cervical cancer cell lines showed repressed expression of SOCS1, SOCS3, and SOCS5." (PMID 25849377, 2015). "In contrast, no DNA methylation was detected in the SOCS3 and SOCS5 promoter region, at least in the CpG-enriched region examined in this experiment, of all cervix cancer cell lines." (PMID 25849377, 2015).
cholangiocarcinoma (6 papers, 2009 to 2022). A carcinoma that arises from the intrahepatic biliary tree (intrahepatic cholangiocarcinoma) or from the junction, or adjacent to the junction, of the right and left hepatic ducts (hilar cholangiocarcinoma). "In human cholangiocarcinoma, sustained IL-6/Stat3 signalling, enhanced Mcl-1 expression and resistance to apoptosis, is attributed to epigenetic silencing of SOCS3 by promoter hypermethylation." (PMID 19698101, 2009). "On the other hand, STAT3 hyperactivation [as in cholangiocarcinoma (CCA)] determines an epigenetic silencing of the SOCS3 gene and cellular resistance to apoptosis and induction of EMT." (PMID 35047557, 2021). "As an antagonist of the JAK/STAT pathway, suppressor of cytokine signaling 3 (SOCS3) plays an integral role in shaping the inflammatory environment, tumorigenesis and disease progression in cholangiocarcinoma (CCA); however, its prognostic significance remains unclear." (PMID 26485275, 2015).